CAT (catalase)
Diseases named in the same sentence as CAT in open-access papers (continued):
Sharing a sentence is not in itself a finding about the gene and the disease.
prostate carcinoma (continued). "Similarly, in patients with prostate cancer, lung transplantation, cirrhosis, chronic kidney disease, acute kidney disease, tomography exposure and MR exposure; low values of MDA (1.2800-2.9550) are associated with high values of SOD (3.2400-5.7790), CAT (0.0697-0.5630) and GSH (0.0010-0.0049)." (PMID 35720997, 2022). "In this study, we analyzed the activity of GST (in plasma), the activity of SOD and CAT, and the concentration of MDA (in serum) in 66 patients with prostate cancer and in 64 controls." (PMID 34409535, 2022). "By using the PEG-catalase compound that only scavenges extracellular H2O2, we demonstrated that intracellular H2O2 is the determinant factor of prostate cancer cell growth inhibition." (PMID 32512786, 2020). "We examined the effects of kurarinone on the mRNA expression levels of antioxidant enzymes, including superoxide dismutase (SOD), HO-1, glutathione peroxidase (GPX), and catalase (CAT), in human prostate cancer PC3 cells." (PMID 32916869, 2020). "In agreement with previous observations reported for prostate cancer cells, 10 μM PN decreased in MDA-MB231 sphere cells both MnSOD and catalase levels." (PMID 27077810, 2016). "Further to define the role of ROS-Calcium Stress mediated modulation of mitochondrial membrane potential, we had pretreated prostate cancer with ROS scavengers (NAC,GSH or Catalase) and the calpain inhibitor calpeptin as described in material methods." (PMID 25879420, 2015). "CuZnSOD, MnSOD and catalase had lower expression in high grade prostatic intraepithelial neoplasia (PIN) and prostate carcinoma than in benign epithelium." (PMID 24213319, 2012). "Similarly, in prostate cancer, studies have shown that genes involved in oxidative stress response, such as SOD2 (superoxide dismutase 2) and CAT (catalase), play critical roles in determining the tumor’s response to radiotherapy." (PMID 40652278, 2025). "Numerous studies have demonstrated an imbalance in oxidative stress/redox status and a compromised GPX/Thiol antioxidant system in prostate cancer patients, accompanied by reduced activities of superoxide dismutase (SOD), GPX, GSH, and catalase (CAT) compared to controls." (PMID 37765058, 2023). "Plasmids incorporating the CAT gene under the control of an AR responsive promoter and wild-type AR were co-expressed with either empty vector, wild-type MID1 or mutant MID1 expression vectors in the AR-negative prostate cancer cell line PC-3." (PMID 24913494, 2014). "A short (24 h) exposure of DU145 prostate cancer cells to millimolar concentrations of BA (6–16 mM) was able to reduce cell viability and induce oxidative stress by decreasing superoxide dismutase (SOD) and catalase (CAT) activities and the levels of intracellular glutathione." (PMID 37372032, 2023). "In the absence of significant changes in the activity of GST and CAT, it supports the hypothesis that oxidative stress is moderately intense in patients with prostate cancer." (PMID 34409535, 2022). "Reduced expression levels of antioxidants such as catalase, mitochondrial manganese superoxide dismutase (MnSOD), CuZnSOD, and reduced glutathione (GSH), not surprisingly, have been shown in human prostate cancer patient specimens, including tissue samples." (PMID 41008967, 2025). "Finally, we observed a clear co-localization of MCT2 with Catalase (a well-known peroxisome marker) confirming that in PCa MCT2 preferentially localizes at peroxisomes rather than mitochondria in prostate cancer cells." (PMID 26035357, 2015).
vitiligo (51 papers, 2009 to 2025). Generalized well circumscribed patches of leukoderma that are generally distributed over symmetric body locations and is due to autoimmune destruction of melanocytes. "The SNP rs7943316 has been linked to reduced catalase activity, which can exacerbate oxidative stress in melanocytes and is thought to increase the risk of vitiligo." (PMID 40837363, 2025). "Several polymorphisms affecting antioxidant enzymes, such as CAT and GPx, have been identified in vitiligo patients, suggesting an inherent vulnerability and predisposition to oxidative damage." (PMID 41157208, 2025). "Previous studies indicate that the CAT gene rs7943316 SNP locus is associated with increased risks of diseases such as vitiligo and hearing loss, with rare reports on its correlation with asthma onset." (PMID 40433469, 2025). "A slower proliferation of melanocytes was observed in patients with vitiligo than in controls, and a dysregulated redox balance was associated with decreased expression of catalase." (PMID 37109666, 2023). "We excluded the fourth SNP C-262T in CAT, which has also been linked to vitiligo, due to lower band sizes after digestion with SmaI between the C (143/38 + 9 bp) and T (143/47 bp) genotypes." (PMID 37109666, 2023). "Preliminary data from case–control and family studies have revealed a genetic link between CAT and vitiligo susceptibility, suggesting that reduced catalase enzyme activity is caused by mutations in the CAT gene." (PMID 37109666, 2023). "Topical application of Pseudocatalase, a complex able to produce O2 and H2O from H2O2 at a rate higher than catalase, aims to recover the deficiency of catalase activity in vitiligo skin." (PMID 36359263, 2022). "Further, the topical application of catalase of has been proposed to treat the inflammatory disease vitiligo, which is associated with reduced levels of catalase and increased concentrations of H2O2 in the epidermis of the depigmented skin site." (PMID 31126113, 2019). "The variant with CAT -89A/T has been reported to be associated with a significantly reduced level of catalase with a correlation with developing vitiligo in the Chinese population." (PMID 31827713, 2019). "This protocol is of particular biological relevance for the skin disorder vitiligo, which is associated with low levels of catalase and accumulation of H2O2 in the epidermis." (PMID 31126113, 2019). "The combined exposure of UVB, H2O2, and NaN3 is of particular biological relevance for the skin depigmentation disorder vitiligo, which is associated with low levels of catalase and accumulation of H2O2 in the epidermis." (PMID 31126113, 2019). "−89 A/T polymorphisms of catalase in vitiligo patients showed significantly increased lipid peroxidation levels." (PMID 29456788, 2017). "The frequency of the wild and combined genotypes of the T/C exon 9 polymorphism of CAT gene among vitiligo patients and the association with risk of vitiligo." (PMID 24915010, 2014). "In vivo oxidative stress has been attributed to a massive accumulation of H2O2 in vitiligo skin, which is associated with impaired catalase and glutathione peroxidase activities." (PMID 23555779, 2013). "Meta-analysis reported that 389 C/T polymorphisms in the CAT gene may be associated with vitiligo in Caucasians and other ethnicities." (PMID 40837363, 2025). "Genetic polymorphisms, such as catalase gene variations and toll‐like receptor polymorphisms, along with stem cell targets such as melanocytes derived from stem cells, have been implicated in vitiligo onset and possible treatment." (PMID 39624766, 2024). "Several mutations in CAT have been associated with vitiligo symptoms." (PMID 37109666, 2023). "Catalase deficiency in the skin of patients with vitiligo may be caused by tissue-specific changes in gene expression or enzyme structure/function in melanocytes and/or keratinocytes." (PMID 37109666, 2023).
vitiligo (continued). "Based on previous case-control and meta-analysis studies, we assessed the prevalence of three single-nucleotide polymorphisms (SNPs) of the CAT genes A-89T (rs7943316), C389T (rs769217) and C419T (rs11032709) in participants with vitiligo and healthy controls in the Saudi population." (PMID 37109666, 2023). "Moreover, it significantly reduced vitiligo-associated oxidative stress: catalase activity increased to 114% (p < 0.05 vs. placebo) and ROS level decreased up to 60% (p < 0.02 vs. placebo)." (PMID 34356320, 2021). "We and other groups have demonstrated that the CAT -89A/T variants are associated with a significant decrease in CAT activity and a genetic predisposition for vitiligo in both Chinese and Indian population, especially in active and generalized vitiligo patients." (PMID 34977005, 2021). "However, it has been observed that there is an erratic relationship between catalase polymorphism and vitiligo." (PMID 31827713, 2019). "Thus, we investigated CAT exon 9 T/C polymorphism as a candidate susceptibility locus for vitiligo in an Egyptian population." (PMID 24915010, 2014). "Elevations in superoxide dismutase and malondialdehyde, reductions in catalase or catalase gene polymorphism, increases in advanced oxidation protein products, nuclear factor erythroid 2-like 2 (Nrf2) gene polymorphism, and reduced Nrf2 activation are associated with vitiligo susceptibility." (PMID 33918445, 2021). "Increased H2O2 levels have been detected in the epidermis of patients with vitiligo, along with decreased levels of catalase and increased levels of superoxide dismutase (SOD)." (PMID 39947468, 2025). "Several studies have confirmed that catalase levels in the epidermis of patients suffering from vitiligo are lower than those in healthy controls." (PMID 38483584, 2024). "Among the endogenous antioxidants found altered in individuals with vitiligo are the enzymes catalase (CAT), SOD, and GPx, and some vitamins such as C and E." (PMID 39735711, 2024). "Other studies demonstrated high levels of hydrogen peroxide and low levels of catalase in the epidermis and peripheral blood of patients with active stages of vitiligo when compared to healthy individuals." (PMID 39735711, 2024). "Various antioxidants like polypodium leucotomos, ginkgo biloba, catalase/superoxide dismutase, and vitamin E have potential in vitiligo." (PMID 38136202, 2023). "The delta coefficient (D’) was calculated for both vitiligo patients and controls for three SNPs, namely, rs7943316, rs769217, and rs11032709, in the CAT gene." (PMID 37109666, 2023). "Nrf2 and its downstream detoxification genes were found to be upregulated in epidermal skin lesions of subjects with vitiligo, and catalase protein expression and activity are low in the epidermis of patients with vitiligo compared to healthy controls." (PMID 36980277, 2023). "In a randomized trial, objective vitiligo repigmentation obtained with topical catalase/dismutase superoxide (C/DSO) treatment is similar to topical 0.05% betamethasone, highlighting the need for better antioxidant medications." (PMID 36980277, 2023). "Numerous studies have confirmed increased erythrocyte superoxide dismutase (SOD), superoxide dismutase in the skin, and decreased skin catalase levels in vitiligo patients." (PMID 38136202, 2023). "Because vitiligo patients have been found to have decreased catalase enzyme activity throughout their epidermis, CAT is a candidate gene in vitiligo, and was selected for our study." (PMID 37109666, 2023). "Patients with vitiligo show decreased catalase activity and increased deposition of excess H2O2 throughout the epidermis; hence, CAT gene mutations have been implicated in vitiligo." (PMID 37109666, 2023). "Several studies documented high concentrations of H2O2 and peroxynitrite and reduced levels of the antioxidant enzymes catalase, glutathione reductase, thioredoxin/thioredoxin reductase, and methionine sulfoxide reductases in vitiligo skin." (PMID 36359263, 2022).
vitiligo (continued). "The ROC curve analysis for vitiligo diagnosis was significant for CAT, MDA, and 8-OHdG, displaying areas under the curve of 0.772, 0.718, and 0.802, respectively but not for SOD and TAC." (PMID 34977005, 2021). "In patients with vitiligo, in order to compensate for low catalase levels, PC-KUS was introduced for removal of overproduced epidermal H2O2." (PMID 34356320, 2021). "It is worth noting that previous studies have observed controversial serum CAT activity in vitiligo patients, although most studies have observed reduced CAT activity in vitiligo." (PMID 34977005, 2021). "In in vivo situations,when the skin is affected by various skin disorders (vitiligo, xeroderma pigmentosum etc.), catalase activity isdownregulated resulting in elevatedH2O2 concentrations in theepidermis." (PMID 33188446, 2020). "Low levels of antioxidants, such as catalase, glutathione peroxidase, and superoxide dismutase are reported in the epidermis and serum of vitiligo patients." (PMID 32277157, 2020). "Various studies have shown that the catalase levels in the epidermis of vitiligo patients are lower as compared to those of the healthy control subjects with a resultant increase in the concentration of hydrogen peroxide." (PMID 31827713, 2019). "Suction blister roofs taken from the involved and uninvolved epidermis of patients with vitiligo showed a consistent reduction in levels of catalase compared to normal healthy controls of matched photo-skin types." (PMID 28018522, 2016). "Several studies have shown the level of catalase decreased in the skin of vitiligo patients and the concentration of H2O2 in the epidermis was much higher than normal." (PMID 28018522, 2016). "Our results are consistent with previous studies demonstrating that higher Nrf2-dependent transcriptional activity is required for the maintenance of redox balance in vitiligo skin and that catalase protein expression and activity are low in vitiligo skin." (PMID 23555779, 2013). "At the protein level vitiligo and healthy melanocytes showed similar staining intensity for catalase, whereas SOD2 labeling was slightly lower in vitiligo cells." (PMID 23555779, 2013). "Therefore, we focused on the sensitivity of KCs to H2O2-induced oxidative stress in vitiligo lesions with high epidermal H2O2 levels accompanied by reduced catalase and increased SOD activity." (PMID 39947468, 2025). "Patients with vitiligo exhibit lower CAT activity, suggesting a compromised antioxidative defence." (PMID 40837363, 2025). "Vitamin D, vitamin E, zinc, copper, piperine, pseudo catalase and other vitamins/herbals may improve vitiligo outcomes primarily through antioxidant supplementation pathways." (PMID 39624766, 2024). "Hence, growth factors and catalase, as well as other compensating media, are needed to culture melanocytes from patients with vitiligo." (PMID 37109666, 2023). "Another meta-analysis confirmed a negative association between C389T (rs769217) in CAT and vitiligo." (PMID 37109666, 2023). "However, additional statistical analysis should be performed in studies with large sample sizes, and meta-analysis studies are recommended for the study of the remaining SNPs and their relationship with vitiligo in the CAT gene." (PMID 37109666, 2023). "For vitiligo, most studies were performed with (pseudo)catalase or superoxide dismutase." (PMID 38136202, 2023). "Therefore, the current study aimed to evaluate the prevalence of SNPs in the CAT gene and vitiligo in Saudi patients." (PMID 37109666, 2023). "Few studies have investigated the association between vitiligo susceptibility and SNPs in the CAT gene, and in the Saudi population, it has not been investigated so far." (PMID 37109666, 2023). "The level of ROS increases in the skin lesions of vitiligo, while the expression of antioxidant enzymes such as catalase (CAT), glutathione reductase (GPX), thioredoxin (Trx)/thioredoxin reductase (TrxR), and methionine sulfoxide reductase (Msr) A and B is downregulated." (PMID 35103096, 2022).
vitiligo (continued). "Some studies have searched for the possible association between the 389C > T polymorphism (rs769217) in the CAT gene and the risk of vitiligo, while others reported a lack of this relationship." (PMID 36555526, 2022). "In addition to high mitochondrial ROS emission, vitiligo patients have a deficient EAS, with low activity and low gene expression of catalase (CAT), glutathione peroxidase (GPx), and thioredoxin reductase (TrxR), leading to a chronic OS state." (PMID 35360245, 2022). "However, the sensitivity of using serum CAT or MDA cutoff values for vitiligo diagnosis was relatively low, about 45% and 32%, respectively." (PMID 34977005, 2021). "Whereas, in Indian patients, the CAT –262G/A variant showed no change in CAT activity or risk of vitiligo." (PMID 34977005, 2021). "In addition, patients with vitiligo have down-regulated enzymes, such as catalase (CAT) and dysregulated superoxide dismutase (SOD), and abnormal non-enzyme defense to oxidants like the total antioxidant capacity (TAC)." (PMID 34977005, 2021). "Meanwhile, the levels of SOD, CAT, and GPx activity are inconsistent with previous in vivo studies on vitiligo, which indicates that the activity of antioxidation enzymes is changing dynamically at different stages of vitiligo." (PMID 32377394, 2020). "Increased malondialdehyde and decreased catalase were found in vitiligo patient blood." (PMID 29456788, 2017). "Although the SNP 389 T/C in the 9th exon of the CAT gene is a silent substitution, some reports have indicated that such SNP could have a role in the disposition for vitiligo in different populations." (PMID 24915010, 2014). "GPX, catalase (CAT), methionine sulfoxide reductase (MSR) A and B, and other antioxidant enzymes have downregulated expression in vitiligo skin lesions." (PMID 40837363, 2025). "Other authors studied the levels of MDA, catalase, GSH-Px, and SOD in the tissues of 10 patients with active vitiligo, 10 patients with stable vitiligo, and 20 matched healthy controls." (PMID 40427437, 2025). "In vitiligo skin, epidermal H2O2 levels are increased, while catalase and SOD levels are decreased and increased, respectively." (PMID 39947468, 2025). "Oxidative stress in the skin led to a sharp decrease in SOD and CAT levels and a significant increase in MDA levels in the vitiligo group." (PMID 38542385, 2024). "A reduced antioxidant capacity was identified in vitiligo patients in this study in the form of decreased TAS, CAT, GPx, and GST." (PMID 37762802, 2023). "Several toxic compounds are thought to be produced during melanogenesis in vitiligo, resulting in H2O2 buildup that inhibits catalase function and promotes melanocyte eradication." (PMID 37762802, 2023). "TAS, CAT, GPx, and GST were significantly lower in vitiligo patients compared to controls (p < 0.05)." (PMID 37762802, 2023). "Current studies have shown high levels of antioxidant activities in active vitiligo cases as compared to stable vitiligo and healthy controls by measuring the levels of the antioxidant enzymes SOD and CAT." (PMID 36980277, 2023). "The redox state imbalance is more prominent in active vitiligo than stable vitiligo, as demonstrated by lower TAS, antioxidant enzyme activities (CAT and GPx), and higher oxidative products (MDA and AOPP)." (PMID 37762802, 2023). "This is consistent with other studies that also detected a decrease in TAS, CAT, GPx, and GST in vitiligo patients." (PMID 37762802, 2023). "In the skin lesions of vitiligo, the expression of GPX, catalase (CAT), and methionine sulfoxide reductase (MSR) A and B, as well as other antioxidant enzymes, is downregulated." (PMID 36980277, 2023). "Our ROC analyses showed that the serum CAT, MDA, and 8-OHdG had a predictive capacity on diagnosis of the vitiligo." (PMID 34977005, 2021). "The control of endogenous H2O2 is crucial, as, in aged human skin and vitiligo conditions, the accumulation of H2O2 along with a reduction in CAT activity has been observed." (PMID 33946757, 2021).